CD4 (CD4 molecule)
Diseases named in the same sentence as CD4 in open-access papers (continued):
Sharing a sentence is not in itself a finding about the gene and the disease.
COVID-19 (continued). "By analyzing single cell transcriptomes, we demonstrate that CD4+ T-cells in severe COVID-19 have an impaired FOXP3-mediated negative feedback, generating CD25+ hyperactivated T-cells, which show multifaceted effector T-cell differentiation and uniquely produce the protease Furin." (PMID 33178221, 2020). "In addition, there is evidence for recruitment of immune cells populations (antibody-secreting cells, T helper cells and activated CD4+ and CD8+ T cells), with IgM and IgG SARS-CoV-2 binding antibodies in the patient’s blood before COVID-19 symptoms are resolved." (PMID 32764275, 2020). "A trend toward higher PD1 expression on CD8+ and CD4+ T cells in COVID-19 could be observed although with no statistical significance." (PMID 32983106, 2020). "Without restimulation with PMA or incubation with monensin, a high percentage of GM-CSF+ and IL-6+ expressions could be found in CD4+ T-cells from COVID-19 patients in both ICU and non-ICU patients compared to healthy controls." (PMID 34676125, 2020). "In addition, in our study we observed significantly lower proportions of both CD4+ and CD8+ RTE cells and naïve cells in COVID-19 X-ray (+) patients compared to the group of healthy volunteers, without differences between COVID-19 X-ray (+) patients and COVID-19 X-ray (−) patients." (PMID 33291439, 2020). "Several studies have shown the responses of T cells from COVID-19 patients to different SARS-CoV-2-derived peptides matching sequences of S and N proteins; these cellular responses included increased expression of several cytokines such as IFN-γ, IL-2, and IL-17 in CD4+ cells." (PMID 33198287, 2020). "The study also presents the quantity and frequency of T cell responses, particularly CD4+ and CD8+; the profile of cytokine production and secretion; and its relation to T cell type, disease severity, and utility in prognostics of the course of SARS, MERS, and COVID-19 outbreaks." (PMID 32916812, 2020). "The underlying pathophysiology of COVID-19 involves a maladaptive immune response to SARS-CoV-2 infection with increased levels of IL-6, IL-10, IL-2 and TNFα produced by macrophages, and fewer CD4+ and CD8+ T cells, but no significant changes in B-cell counts." (PMID 32399655, 2020). "Meanwhile, TNF-α was not significantly upregulated in CD4+ T-cells from COVID-19 patients." (PMID 34676125, 2020). "Besides specialized research labs, however, there is limited ability to measure HCoV CD4+ and CD8+ T-cell responses to SARS-CoV-2 infection, which currently impedes interpretation of any potential correlation between COVID-19 disease pathogenesis and the calibration of pandemic control measures." (PMID 33392109, 2020). "In addition to case severity and death rate, the immune status of the two groups of COVID-19 patients in our study also differs, as revealed by the significantly lower counts of CD3, CD4, CD8, CD19 and percentages of CD3, CD4, CD8, CD16+56 in the aged group compared to the other group." (PMID 33106442, 2020). "Collectively, CD4+ T-cells from severe COVID-19 patients are hyperactivated and FOXP3-mediated negative feedback mechanisms are impaired in the lung, which may promote immunopathology." (PMID 33178221, 2020). "Between 3 and 17% of COVID-19 patients developed acute respiratory distress syndrome (ARDS), as a result of hyper inflammation (excessive infiltration of activated innate immune cells and cytokine release syndrome) and lymphocytopenia (reduced levels of CD4+, CD8+, and B cells)." (PMID 33335518, 2020). "In addition, single-cell TCR (sc-TCR) analysis revealed increased clonal expansion levels in several CD4+ but not CD8+ T cell subsets in severe COVID-19 than those in mild cases." (PMID 33101705, 2020). "However, compared with mild cases, severe COVID-19 cases had lower levels of CD4+ T cells [146/μL (IQR, 107–277)] and an even more significant reduction in CD8+ T cells [only 59/μL (IQR, 33–109)], which has a sharper drop than CD4+ T cell." (PMID 32983157, 2020).
COVID-19 (continued). "The CD4+ T cells showed significant staining for IFN-γ, with five out of six subjects generating IFN-γ+CD4+ T cells responses to at least one of the SARS-CoV-2 peptide N, M, or S pools, indicating that convalescent COVID-19 patients have solid SARS-CoV-2−specific CD4+ T cell immunity." (PMID 32913053, 2020). "Furthermore, serum concentrations of IL-10, IL-6, and TNF-α were significantly lower in patients in the disease resolution in comparison to the disease period, whereas the total number of T cells, CD4+ T cells, and CD8+ T cells was restored during the decline period of COVID-19." (PMID 32916812, 2020). "Previous studies indicated that SARS-CoV-2 infections could lead to dysregulation of the levels of lymphocyte subsets, by showing that the absolute counts of CD3+ T cells, CD4+ T cells, CD8+ T cells, CD19+ B cells, and CD56+ NK cells were reduced in patients with COVID-19." (PMID 33274223, 2020). "However, whereas about two-thirds of COVID-19 patients had KI67+ non-naïve CD4 or CD8 T cell frequencies above controls, about one-third had no increase in frequency of KI67+ CD4 or CD8 T cells above that observed in HDs." (PMID 32669297, 2020). "Only CD4+ T cells in COVID-19 showed a higher frequency of PD1+LAG-3− and PD1+TIM-3− T cells compared to healthy donors although the frequency of these cells was highest in malaria with a significant increase of both PD1+LAG-3− and PD1+TIM-3− on CD8+ and CD4+ T cells compared to healthy controls." (PMID 32983106, 2020). "The significantly decreased levels of CD4+ T lymphocytes and ratio of CD4+/CD8+ lymphocytes and the significantly increased levels of TNF-α and IL-6 in the peripheral blood can be used as important laboratory indicators to assess the severity of COVID-19 in patients." (PMID 32976531, 2020). "(a–d) Representative flow cytometry plots showing the expression of activation and proliferation markers on CD4+ and CD8+ T cells (respectively in a, b), TCR-γδ T cells (c) and NK cells (d: plots shown for NK CD56dim cells) in a healthy control and the COVID-19 patient (at days 23 and 58)." (PMID 33331820, 2020). "In the kidney tissues, CD4+ T cells and CD56+ natural killer cells were hardly found in the kidney interstitium; however, severe infiltration of CD68+ macrophages (6/6 cases) and moderate CD8+ T cells (2/6 cases) were observed in six post-mortem examinations of patients with COVID-19." (PMID 33317643, 2020). "Stimulating peripheral blood mononuclear cells from COVID-19 convalescent patients with overlapping peptides from severe acute respiratory syndrome coronavirus 2 (SARS-CoV-2) led to the clonal expansion of SARS-CoV-2−specific CD8+ and CD4+ T cells in vitro, with CD4+ T cells being robust." (PMID 32913053, 2020). "In addition, a significant reduction in both CD4+ T cells and CD8+ T cells were specifically observed in patients with severe COVID-19 and severe influenza A. Therefore, this indicates a more severe immune insult in patients with the severe form of the disease." (PMID 33261583, 2020). "Thus, PWH, regardless of CD4 cell count or viral load, should receive primary vaccination against COVID-19 and ongoing updated doses to prevent severe health outcomes and protect against emerging variants as recommended by the Centers for Disease Control and Prevention (CDC)." (PMID 41214612, 2025). "Likewise, a study conducted in Jordan that contrasted T cell-mediated immunity and side effects of mRNA vaccines with conventional COVID-19 vaccines reported that the Pfizer-BioNTech vaccine induced higher helper CD4+ T cell responses compared to non-Pfizer-BioNTech vaccines." (PMID 41157248, 2025). "Percentages of CD4+, Th17, Treg cells and the Th17/Treg ratio were not significantly different between vaccine timing groups (0-3 months, 3-6 months, 6-9 months, 9-12 months, > 12 months between COVID-19 vaccination and sampling) and a reference group of never vaccinated participants." (PMID 38504979, 2024).
COVID-19 (continued). "CD4 and CD8 T-cell responses are unaffected by B-cell-depleting therapies, which may explain why some of these patients have less severe COVID-19 infection, especially if they have been previously vaccinated against COVID-19 and were able to mount some level of active immune response." (PMID 38391780, 2024). "To determine whether COVID-19 mRNA vaccination induced changes in HIV reservoir size (defined as genome-intact proviral load), defective proviral burden or total HIV DNA load, we quantified the number of intact, defective and total proviral copies per million CD4+ T-cells." (PMID 38224350, 2024). "The SARS-CoV-2-specific polyfunctional Th1 CD4 T cell response (characterized by the co-expression of IFN-γ, TNF-α and/or IL-2), as seen in seropositive children, may be necessary for effective viral control and has been documented in COVID-19 convalescent adults." (PMID 38235336, 2024). "Thus, future studies should investigate tissue-resident CD4+ and CD8+ T cells in the lungs to determine whether their frequency and function correlate with protection from symptomatic and fatal infections in unvaccinated COVID-19 patients." (PMID 38605956, 2024). "In the context of SARS-CoV-2 infection, there are indications that both increased senescence of CD4+ and CD8+ T cells, as well as the overall reduced proportions of these cell types in patients with diabetes may have contributed to the observed increase in severe COVID-19." (PMID 38214784, 2024). "It is reported that SARS CoV-2 infection mainly affects T lymphocytes (especially CD4 + T and CD8 + T cells), which means that T lymphocytes may be highly involved in the pathological process of COVID-19 and provide an important means of defense against COVID-19." (PMID 38822405, 2024). "Therefore, we shortlisted 18 (12 studies for COVID-19 convalescent subjects and 8 studies for vaccinated subjects) research articles containing 89 different datasets in which OX40 and CD137, CD69 and CD137 were used to measure spike-specific CD4+ and CD8 + T cells response respectively." (PMID 38167915, 2024). "However, the characteristics of cross-reactive memory CD4+ and CD8+ T cells associated with subsequent protection of asymptomatic COVID-19 patients (i.e., unvaccinated individuals who never develop any COVID-19 symptoms despite being infected with SARS-CoV-2) remains to be fully elucidated." (PMID 38318166, 2024). "Similarly, we did not observe a clear difference in the vaccine-induced CD4+T cell responses that could discriminate between the PI group (with or without symptomatic COVID-19)." (PMID 39104410, 2024). "Hence, the expression of CD38+ on CD3+CD8+ cells with or without simultaneous expression of PD1 on CD3+CD4+ cells may be utilized as a biomarker of a fatal outcome in hospitalized patients with COVID-19." (PMID 36992243, 2023). "Moreover, the trend of reduction in the CD4/CD8 ratio that was found in the EVs of COVID-19 patients with severe disease was also demonstrated in studies that described the changes in the peripheral lymphocytes and inflammatory cytokines in COVID-19 patients in general." (PMID 36982991, 2023). "Because they seem to be at a greater risk of severe consequences and mortality from COVID-19 than other people, the World Health Organization advises that PLHIV should be a designated priority group in the national COVID-19 vaccination program, regardless of their CD4 level." (PMID 37891225, 2023). "ART inhibits HIV-1 replication and slows the elimination of memory CD4+ T cells and memory B cells, which may explain the similar frequencies of memory CD4+ T cells and memory B cells in HIV-1+ individuals when compared to COVID-19 patients and healthy donors, respectively." (PMID 36992700, 2023).
COVID-19 (continued). "Although little has been written about the specific role of MT-CO3 in CD4+ T cells, according to the important role of MT-CO3 gene in the immune response and its involvement in aerobic respiratory energy supply, MT-CO3 gene may show differential expression after COVID-19 vaccination." (PMID 36936955, 2023). "In conclusion, our findings revealed that there was a negative impact of COVID-19 on the absolute numbers of CrAg tests performed, as well as an increase in detection rate in certain provinces, probably reflecting only severely ill patients with very low CD4 counts, presenting themselves for care." (PMID 37768950, 2023). "Indeed, the patient displayed absence of circulating CD4 + T cells specific for a pool of peptides spanning the spike, membrane, and nucleoprotein proteins, as compared to a non-infected individual and a subject with history of paucisymptomatic COVID-19." (PMID 35779200, 2022). "Therefore, as Q-VD prevents CD8 T cell apoptosis, it could be a valuable tool for COVID-19 patients, not just by rescuing CD4 T cells but also by directly or indirectly improving the effector CD8 T cells." (PMID 35066575, 2022). "However, several studies have reported that the COVID-19 vaccine shows high interpersonal variability in terms of humoral and cellular responses, such as those with respect to SARS-CoV-2 spike protein immunoglobulin (Ig)G, IgA, IgM, neutralizing antibodies, and CD4+ and CD8+ T cells." (PMID 35455312, 2022). "She demonstrated that SARS-CoV-2-reactive CD4+ memory T cells were present in unexposed individuals, displaying low functional avidity and multiple, highly variable cross-reactivities, e.g., towards common cold coronavirus, which were not present COVID-19 patients." (PMID 36225392, 2022). "The lack of difference in severe COVID-19 breakthrough illness risk between PWoH and PWH with higher CD4 cell counts may be associated with engagement in medical care, different health care–seeking behaviors, and reduced comorbidities among the PWH included compared with PWoH." (PMID 36227594, 2022). "Furthermore, donors with milder disease were associated with polyantigenic CD4+ T cell responses that recognized more prominently non-S proteins in addition to S, while severe acute COVID-19 was characterized by lower magnitudes of CD4+ T cell responses and a narrower repertoire." (PMID 35806161, 2022). "Furthermore, severe COVID patients have lower levels of circulating IFN-γ as well as reduced frequencies of CD4+ and CD8+ T cells as compared to those with moderately severe pathology, and polyfunctional Th1 cells are present in lower frequencies in patients with COVID-19." (PMID 35572514, 2022). "However, several studies have reported that the COVID-19 vaccine shows high interpersonal variability in terms of humoral and cellular responses, such as those with respect to anti-SARS-CoV-2 spike immunoglobulin (Ig)G, IgA, IgM, neutralizing antibodies, and CD4+ and CD8+ T cells." (PMID 35455312, 2022). "In addition to decreased levels of CD3+/CD4+ T lymphocytes, CD3+/CD8+ T lymphocytes and CD19+ B lymphocytes, CD16+/CD56+ NK cells were also decreased in the peripheral blood of COVID-19 patients, and these cells may play critical roles in the inflammatory cytokine storm." (PMID 35619076, 2022). "Therefore, the levels of CD4+ and CD8+ T cells might be good biomarkers of COVID-19." (PMID 36263178, 2022). "That CD4+ T cells are more prone to undergo apoptosis may also contribute to the development of “helpless” CD8+ T cells, which are exhausted and shorter-lived cells, leading to defective T cell toxicity and death of CD8+ T cells in patients with severe COVID-19." (PMID 35581387, 2022). "We showed in this study that COVID-19 did not induce a concomitant activation of M. tuberculosis–specific CD4+ T cells, suggesting that acute SARS-CoV-2 infection may not immediately result in progression of latent M. tuberculosis to subclinical or active TB disease." (PMID 33945513, 2021).
COVID-19 (continued). "Some patients with severe or moderate COVID-19 show a deficient expression of IFN-γ in CD4+ T lymphocytes, CD8+ T lymphocytes, and NK cells; however, lower levels of IFN-γ expression by CD4+ T lymphocytes are found in those with severe rather than moderate COVID-19." (PMID 34360684, 2021). "Finally, to address potential positive or negative effects of preexisting cross-reactive memory T cells, we compared 25-μg mRNA-1273 COVID-19 vaccine responses between subjects with or without measurable preexisting SARS-CoV-2 spike–reactive memory CD4+ T cells." (PMID 34519540, 2021). "Differences in the immunological parameters among COVID-19 and non-COVID-19 cases were explored by a univariate linear-log regression model and a multivariate model adjusted by age: the two groups differed in their percentages of both T (CD4 and CD8) and B-activated cells and Tregs and Bregs." (PMID 34659235, 2021). "Interestingly, the correlation between CD4+ T and CD8+ T proportions showed a negative association in all three groups (nCoV, VP, and HC) except that non-significant correlation was found in female COVID-19 patients, for unclear reasons." (PMID 33350432, 2021). "Notably, excluding CD4-GMZB, the Th1-like CD4-GZMK subset dominated in the expanded CD4+ T cell compartment in non-severe COVID-19 cases, but only represented a minor subset in severe cases, indicating a discordant CD4+ T cell responses likely underlying the development of severe COVID-19." (PMID 35095917, 2021). "Interestingly, compared with healthy individuals, COVID-19 patients have higher numbers of CD57+ and/or PD-1+ (also CD28null) senescent/exhausted T-cells in both CD4+ and CD8+ compartments, suggesting that COVID-19 may also lead to the development of senescent/exhausted T-cells." (PMID 34680058, 2021). "Notably, in severe/critical COVID-19 patients in the recovery stage, the proportion of CD14 monocytes (based on the expression of the marker genes CST3, LYZ, CD14) in PBMCs were elevated, but CD4 T cells (IL7R, LTB) were decreased, consistent with a previous report." (PMID 35046942, 2021). "Moreover, reduced CD3+, CD4+ and CD8 + T cell counts could reflect the severity of the COVID-19." (PMID 34876159, 2021). "In contrast to CD4+ T cells, we found a reduction of naïve CD8+T cells that was followed by a relative increase in percentage, but not in total number of effector memory CD8+T cells, suggesting that naïve CD8+T cell could have been the dominant responders in severe COVID-19 patients." (PMID 33692788, 2021). "Last, because it is known that CD4+ T cells are necessary for regulating the magnitude and quality of the cytotoxic CD8+ T cell response, we investigated the molecular mechanisms by which TRM17 might regulate the CD8+ T cell cytotoxic response in patients with COVID-19." (PMID 33622974, 2021). "Interestingly, the numbers of total T cells, CD4+ T and CD8+ T cells are negatively correlated to levels of TNF-α, IL-6, and IL-10, respectively, suggesting these cytokines may be involved in the decrease of T cells detected in COVID-19." (PMID 32425950, 2020). "Considering that CD4+ T cell immunotherapy is a promising approach for treating CD8+ T cell dysfunction in chronic infections and cancer, adoptive therapy with Tregs may be an effective strategy for COVID-19 treatment by balancing inflammation in the lung tissue." (PMID 32712629, 2020). "We suspected that the disturbed T cell compartments may contribute to COVID-19 immunopathogenesis, e.g., the impaired antiviral responses by innate-like T cells and CD8+ T cells, meanwhile amplifying inflammation and inducing aberrant antibody responses by CD4+ T cells." (PMID 33101705, 2020). "Moreover, the number of immunosuppressive T-regulatory, T-reg (CD4+CD25+Foxp3+) cells and concentrations of IL-6, IL-10, and C-reactive protein (CRP) were up-regulated in patients with severe COVID-19, suggesting that SARS-CoV-2 infection may lead to “over-immunosuppression” in the case of obesity." (PMID 32650509, 2020).